DDX24 (DEAD-box helicase 24)
Description:
ATP-dependent RNA helicase that plays a role in various aspects of RNA metabolism including pre-mRNA splicing and is thereby involved in different biological processes such as cell cycle regulation or innate immunity. Negatively regulates cytosolic RNA-mediated innate immune signaling at least in part by affecting RIPK1/IRF7 interactions. Alternatively, possesses antiviral activity by recognizing gammaherpesvirus transcripts in the context of lytic reactivation. Plays an essential role in cell cycle regulation in vascular smooth muscle cells by interacting with and regulating FANCA (Fanconi anemia complementation group A) mRNA (By similarity). (Microbial infection) Plays a positive role in HIV-1 infection by promoting Rev-dependent nuclear export of viral RNAs and their packaging into virus particles.
Tractability: PROTAC: UniProt records ubiquitination sites on it; ubiquitination databases record sites on it; its protein half-life has been measured.
Target class: Enzyme; Hydrolase
Gene: Protein-coding gene on chromosome 14 (94,048,287 to 94,081,215, reverse strand). Ensembl gene ENSG00000089737.
Subcellular location: Cytoplasm; Nucleus
Subcellular location (Human Protein Atlas): Cytosol; Nucleoli
Gene Ontology:
Molecular function: protein binding; RNA binding; RNA helicase activity; ATP binding; ATP hydrolysis activity; nucleic acid binding
Biological process: RNA metabolic process
Cellular component: cytoplasm; membrane; nucleolus; nucleus
Genetic constraint (gnomAD): Loss-of-function variants: 27 observed, 71.5 expected, observed/expected ratio (o/e) 0.38, 90% interval 0.28 to 0.52. The upper end of that interval is the gene's LOEUF score, 0.52, which puts it in group 2 of 6, group 1 being the genes least tolerant of losing a copy. Missense variants: 971 observed, 1,070.7 expected, observed/expected ratio (o/e) 0.91, 90% interval 0.86 to 0.96. Synonymous variants: 387 observed, 397.8 expected, observed/expected ratio (o/e) 0.97, 90% interval 0.89 to 1.06.
Homologues: Orthologues: chimpanzee DDX24 (99% identical), macaque DDX24 (97% identical), dog DDX24 (84% identical), rabbit DDX24 (81% identical), guinea pig DDX24 (81% identical), pig DDX24 (80% identical), rat Ddx24 (80% identical), mouse Ddx24 (79% identical), tropical clawed frog ddx24 (52% identical), zebrafish ddx24 (47% identical), Drosophila melanogaster CG9143 (35% identical), Caenorhabditis elegans F55F8.2 (31% identical). Paralogues in human: DDX27 (18% identical), DDX18 (18% identical), DDX46 (17% identical), DDX17 (17% identical), DDX42 (17% identical), DDX43 (17% identical), DDX54 (17% identical), DDX3X (17% identical), DDX3Y (17% identical), DDX41 (17% identical), DDX21 (17% identical), DDX31 (17% identical), and 26 more.
Diseases named in the same sentence as DDX24 in open-access papers:
DDX24 is named in the same sentence as 30 diseases in open-access papers, as found by Europe PMC text mining. Sharing a sentence is not in itself a finding about the gene and the disease. The quoted sentences say what the papers report.
breast carcinoma (3 papers, 2017 to 2022). "Analysis of publicly available expression profiles of human tumors showed that high level of DDX24 expression correlates with decreased survival of HER2 positive breast cancer and gastric cancer patients." (PMID 28223711, 2017). "Analysis of expression of DDX24 in human tumors suggests that high level of the gene expression correlates with a lower survival rate of Gastric and HER2+ positive breast cancer patients." (PMID 28223711, 2017). "This is consistent with reports that DDX24 depletion inhibits the growth of multiple cancer cell lines and that its overexpression correlates with a lower survival rate in gastric and HER2-positive breast cancer patients." (PMID 30367141, 2018).
gastric cancer (3 papers, 2017 to 2025). A primary or metastatic malignant neoplasm involving the stomach. "Its involvement in cancer is multifaceted, previous studies have linked DDX24 to liver cancer progression through stabilization of LAMB1 mRNA 39-40, and gastric cancer growth." (PMID 39897555, 2025). "DDX24 was identified as a drug target in cancer therapeutics by screening of a shRNA library, which was agreed with the report by Li F in gastric cancer." (PMID 35370459, 2022).
hepatocellular carcinoma (3 papers, 2022 to 2023). A malignant tumor that arises from hepatocytes. "Previously, many studies have found that DHX9, DHX15, DDX24, DHX29, etc. are widely involved in tumor progression through various pathways, however, the role of DHX37, as an important member of the DEAD/H-box RNA helicase family, in hepatocellular carcinoma progression has been less studied." (PMID 37958405, 2023).
lung cancer (3 papers, 2022 to 2025). A malignant neoplasm involving the lung. "Collectively, these findings suggest that loss of DDX24 suppresses lung cancer progression by stimulating autophagy through promoting the production of IKBKG-L." (PMID 39897555, 2025). "Collectively, our data strongly support the notion that DDX24 is overexpressed in lung cancer and its elevated expression is associated with poor patient prognosis, implicating DDX24 as a potential driver of lung cancer progression." (PMID 39897555, 2025). "Functional studies using DDX24-deficient lung cancer cell lines demonstrated impaired tumor growth both in vitro and in vivo." (PMID 39897555, 2025). "A comprehensive analysis of RBPs implicated DDX24 in autophagy regulation, prompting a deeper investigation into its role in lung cancer." (PMID 39897555, 2025). "To elucidate the underlying mechanism, we generated DDX24-deficient lung cancer cell lines." (PMID 39897555, 2025). "Loss of DDX24 suppresses lung cancer growth by promoting autophagy." (PMID 39897555, 2025). "Our results suggest that DDX24 modulates lung cancer cell proliferation by regulating IKBKG alternative splicing and subsequent autophagy induction." (PMID 39897555, 2025). "Our findings demonstrate that DDX24 suppression promotes autophagy and inhibits lung cancer progression." (PMID 39897555, 2025). "Bioinformatic analysis of the GEO database revealed significantly elevated DDX24 mRNA levels in lung cancer tissues compared to normal lung tissues." (PMID 39897555, 2025). "To elucidate the molecular mechanisms underlying DDX24-mediated autophagy regulation and its impact on lung cancer progression, we performed RNA-sequencing using DDX24 depleted lung cancer cells." (PMID 39897555, 2025). "Together, these data indicate that DDX24 also participates in the regulation of lung cancer metastasis, which is consistent with previous findings." (PMID 39897555, 2025). "Collectively, these data strongly suggest that DDX24 plays a critical role in promoting lung cancer cell growth and proliferation both in vitro and in vivo." (PMID 39897555, 2025). "To investigate the potential role of DDX24 in lung cancer progression, we analyzed its expression levels using multiple datasets." (PMID 39897555, 2025). "This study aims to elucidate the role of DDX24 as a splicing factor that contributes to lung cancer progression via autophagy." (PMID 39897555, 2025). "The precise mechanisms by which DDX24 influences lung cancer metastasis through alternative splicing will be addressed in our future studies." (PMID 39897555, 2025). "In this study, we found that DDX24 depletion significantly impaired the proliferative capacity of lung cancer cells." (PMID 39897555, 2025). "To further validate these observations, we performed Western blot analysis on clinical lung cancer samples, confirming elevated DDX24 protein levels compared to matched normal controls." (PMID 39897555, 2025). "Consistent with its potential oncogenic function, DDX24 protein levels were significantly elevated in lung cancer tissues compared to normal tissues." (PMID 39897555, 2025). "Immunohistochemical staining of tissue microarrays containing lung cancer and adjacent normal tissues (n = 59) independently corroborated these results, demonstrating increased DDX24 immunoreactivity in tumor specimens." (PMID 39897555, 2025). "To elucidate the functional significance of DDX24 in lung cancer, we applied growth curve and colony formation assays and revealed a marked reduction in proliferation and colony forming ability in DDX24-depleted lung cancer cells." (PMID 39897555, 2025). "DDX24, a splicing factor that is significantly elevated in lung tissue, was found to promote autophagy and suppress lung cancer growth when deleted." (PMID 41305005, 2025). "Building on this, we performed transwell assay, and found that DDX24 depletion does inhibit migration and invasiveness of lung cancer cells." (PMID 39897555, 2025).
lung cancer (continued). "Importantly, simultaneous knockdown of IKBKG-L in DDX24-depleted lung cancer cells abrogated the proliferative inhibition induced by DDX24 depletion." (PMID 39897555, 2025). "Previous studies have suggested that DDX24 may play a role in the metastatic process of lung cancer." (PMID 39897555, 2025). "To investigate whether IKBKG-L-mediated autophagy is responsible for depleted DDX24-induced suppression of lung cancer progression, we generated lung cancer cell lines with concurrent knockdown of DDX24 and the long IKBKG isoform." (PMID 39897555, 2025). "Targeting DDX24 may therefore offer a promising therapeutic approach in the treatment of lung cancer." (PMID 41305005, 2025). "Our findings suggest that targeting DDX24 may represent a promising therapeutic strategy for lung cancer treatment, offering new insights into the molecular underpinnings of this disease." (PMID 39897555, 2025). "Moreover, DDX24 expression was inversely correlated with overall survival in lung cancer patients." (PMID 39897555, 2025). "However, the specific role of DDX24 in lung cancer progression remains largely unknown and warrants further investigation." (PMID 39897555, 2025). "Collectively, our results demonstrate that reduced DDX24 expression correlates with increased IKBKG-L production, which subsequently promotes autophagy and suppresses lung cancer cell proliferation." (PMID 39897555, 2025).
HIV-1 infection (2 papers, 2012 to 2018). The type species of lentivirus and the etiologic agent of acquired immunodeficiency syndrome (AIDS). "Our studies suggest that USP7 may play an additional role in HIV-1 infection through its stabilization of DDX24." (PMID 30367141, 2018).
liver cancer (2 papers, 2022 to 2025). An epithelial or non-epithelial malignant neoplasm that arises from the liver. "We divided patients with liver cancer from the TCGA dataset into two groups based on their DDX24 expression." (PMID 36310384, 2022). "To explore the specific function of DDX24 in HCC, we first analyzed 371 liver cancer samples and 50 adjacent samples from The Cancer Genome Atlas (TCGA) database." (PMID 36310384, 2022).
Sepsis (2 papers, 2023 to 2026). Sepsis is defined as life-threatening organ dysfunction caused by a dysregulated host response to infection. "GO analysis of the DE RBPs in sepsis identified terms that were mostly enriched in the immune/inflammatory response; we identified significant differences in 8 down-regulated RBPs in sepsis, including DDX24, CBFA2T2, NOP, ILF3, DNMT1, FTO, PPRC1, NOLC1." (PMID 37749550, 2023). "Overall, the multifaceted study shed light on key roles played by these hub genes (especially DDX24 and GZMM) in the development of sepsis and will be useful references in diagnosing patients and estimating prognosis." (PMID 41948606, 2026). "Thus, the expression levels of the eight RBPs (DDX24, CBFA2T2, NOP14, ILF3, DNMT1, FTO, PPRC1, and NOLC1) were altered in the patients with sepsis might potentially be useful as novel biomarkers as well as targets to facilitate the diagnosis and management of sepsis." (PMID 37749550, 2023).
viral infection (2 papers, 2016 to 2022). "SRS2 group eQTL specificity was also seen for TRIM44, which promotes an enhanced cellular response to viral infection, and DDX24, which encodes a type I interferon-inducible DEAD-box protein RNA-helicase modulating IRF7 activity." (PMID 26917434, 2016). "It is well established that RIG-I interacts with RNAs during viral infection, and therefore we asked whether DDX24 and DDX49 also directly interact with viral RNAs." (PMID 36298642, 2022). "To address whether recognition of KSHV transcripts by DDX24 and DDX49 plays a role in the innate immune response, we tested whether type I interferon is induced in response to KSHV IE and E mRNAs, identified by our RIPseq data, in the absence of viral infection." (PMID 36298642, 2022).
amyloid (1 paper, 2024). "Furthermore, DEAD Box Helicase 17, a similar protein to DDX24, has been implicated in amyloidosis, suggesting that the DEAD box helicase family might influence AD pathology." (PMID 38612434, 2024). "Immunohistochemical studies in AppNL-F mice showed that the increase of DDX24 starts before amyloid pathology or memory impairment is observed." (PMID 38612434, 2024). "We speculate that the advanced amyloid pathology and neurodegeneration decrease DDX24 levels, either through a negative feedback mechanism or because the compensatory function of DDX24 is no longer effective." (PMID 38612434, 2024).
Budd-Chiari syndrome (1 paper, 2023). "Point mutations in the DEAD-box helicase DDX24 are associated with vascular malformations such as multi-organ venous and lymphatic defect (MOVLD) syndrome and Budd-Chiari syndrome, with the pathogenesis largely uncharacterized." (PMID 37705750, 2023).
cervical cancer (1 paper, 2017). A primary or metastatic malignant neoplasm involving the cervix. "Furthermore, the level of DDX24 expression is elevated in cervical cancer tissues and cell lines, relative to normal tissues." (PMID 28223711, 2017).
Cognitive impairment (1 paper, 2024). Abnormal cognition is characterized by deficits in thinking, reasoning, or remembering. "DDX24 was significantly increased in AppNL-F at 6 months of age, i.e., before the appearance of Aβ plaques and the onset of cognitive impairment." (PMID 38612434, 2024). "Thus, the increased levels of DDX24, observed in presymptomatic AppNL-F mice at 6 months of age compared to WT mice, became less prominent over time and were not present in aged mice with cognitive defects." (PMID 38612434, 2024).
colon cancer (1 paper, 2017). "Moreover, significant elevation of the level of DDX24 protein was detected in the majority of tumor cell lines of different origins and in 50% of colon cancer tissues we tested." (PMID 28223711, 2017). "Moreover, DDX24 protein expression is significantly upregulated in two out of four samples of colon cancer tissues relative to normal counterparts." (PMID 28223711, 2017).
intracerebral hemorrhage (1 paper, 2019). A cerebrovascular disorder characterized by bleeding into one or both cerebral hemispheres including the basal ganglia and the cerebral cortex. "More recently, whole-transcriptome analysis in patients with intracerebral hemorrhage correlated to neuroinflammation revealed a connection between DDX24 and Sphingosine 1-phosphate receptor 1 that is a target of the treatment of relapsing MS with Fingolimod." (PMID 31805175, 2019).
Kawasaki disease (1 paper, 2022). A rare inflammatory disease characterized by an acute febrile, systemic, self-limiting, medium-vessel vasculitis primarily affecting children. "In this study, we identified CDR2 as a novel suppressed gene for Kawasaki disease via human transcriptome array analysis and DDX24 associated with CAL formation, which may contribute to further understanding of CAL pathogenesis in KD." (PMID 35204331, 2022). "In this study, we first identified CDR2 as a novel suppressed gene for Kawasaki disease via human transcriptome array analysis, and found DDX24 to be associated with CAL formation—both of which may contribute to further understanding of CAL pathogenesis in KD." (PMID 35204331, 2022).
osteosarcoma (1 paper, 2022). A usually aggressive malignant bone-forming mesenchymal neoplasm, predominantly affecting adolescents and young adults. "The genes DDX24, DDX21, WARS, and IGF2BP2 might play a pivotal role in osteosarcoma, and these genes will be considered as therapeutic targets for osteosarcoma treatment." (PMID 36140189, 2022).
vascular malformation (1 paper, 2023). A non-neoplastic disorder that is the result of defects of vascular morphogenesis. "Previously we identified a DDX24 mutation (DDX24E271K) to be linked to a particular type of vascular malformations, MOVLD17." (PMID 37705750, 2023). "Moreover, the mechanism underlying DDX24 mutation-mediated vascular malformation is still inexplicit." (PMID 37705750, 2023). "Our findings illustrate how DDX24 mutation affects nucleolar structure and function by regulating the phase behavior of NPM1 in the setting of vascular malformation." (PMID 37705750, 2023). "However, the connection between DDX24 and NPM1 in vascular malformation remains elusive." (PMID 37705750, 2023).
cancer (10 papers, 2017 to 2025). A tumor composed of atypical neoplastic, often pleomorphic cells that invade other tissues. "In previous studies, DDX24 was associated with cancer development, viral infection, and vascular malformation." (PMID 35864588, 2022). "DDX24 has garnered increased attention in recent years due to its correlation with cancer development and progression." (PMID 35864588, 2022). "Previous research revealed that DDX24 exhibits either an oncogenic or tumor‐suppressive role in different cancer types." (PMID 35864588, 2022). "With the widespread use of high‐throughput technologies and the advancement in cancer‐related databases, some analyses and predictions can be performed about the function of DDX24 in NSCLC." (PMID 35864588, 2022). "The conflicting RNA-seq (TCGA) and Western blotting results for DDX24 suggests a post-transcriptional regulation of DDX24 expression in cancer cell lines and tumor tissues." (PMID 28223711, 2017). "DDX24, GTPBP4, and BOP1, for example, are involved in RNA metabolism, cell-cycle regulation, and ribosome biogenesis, respectively, reflecting their substantial influence on cellular processes linked to cancer progression." (PMID 39001461, 2024). "Interestingly, DDX24 was a prominent protein in the highest-ranked network (denoted cellular assembly and organisation, cancer, developmental disorder)." (PMID 38612434, 2024). "We show the association of the expression of the identified genes with development and mortality of human cancers and explore the mechanism of the effect of ARCN1 and DDX24 depletion in tumor cells." (PMID 28223711, 2017). "In the majority of cancer datasets available in TCGA the expression level of DDX24 mRNA is not significantly changed relative to corresponding normal tissues." (PMID 28223711, 2017). "It is therefore not surprising that depletion of only three genes – ribosomal protein RPL35A, COPI subunit ARCN1, and RNA helicase DDX24 – selectively inhibited the growth of all three cancer cell lines without strong effects on BJ-hTERT cells." (PMID 28223711, 2017). "Additionally, the genetic alteration status of DDX24 in LIHC, ESCA, CESC and PRAD was low (< 4%) and neither K11E nor E271K mutation was observed in above cancers." (PMID 35370459, 2022). "The siRNA depletion of 3 genes - ARCN1, DDX24, and RPL35A - significantly inhibited the growth of all three cancer cell lines but not normal cells." (PMID 28223711, 2017).